SLC38A5 (solute carrier family 38 member 5)
Description:
Symporter that cotransports neutral amino acids and sodium ions, coupled to an H(+) antiporter activity. Releases L-glutamine and glycine from astroglial cells and may participate in the glutamate/GABA-L-glutamine cycle and the NMDA receptors activation (By similarity). In addition, contributes significantly to L-glutamine uptake in retina, namely in ganglion and Mueller cells therefore, participates in the retinal glutamate-glutamine cycle (By similarity). The transport activity is pH sensitive and Li(+) tolerant. Moreover functions in both direction and is associated with large uncoupled fluxes of protons (By similarity). The transport is electroneutral coupled to the cotransport of 1 Na(+) and the antiport of 1 H(+) (By similarity). May have a particular importance for modulation of net hepatic glutamine flux (By similarity).
Synonyms: JM24; SN2; SNAT5; PP7194
Tractability: Antibody: its Gene Ontology location is reachable by antibodies, with high confidence; UniProt places it where antibodies can reach, with medium confidence; UniProt predicts a signal peptide or a membrane-spanning region; the Human Protein Atlas places it where antibodies can reach. PROTAC: ubiquitination databases record sites on it.
Gene: Protein-coding gene on chromosome X (48,458,537 to 48,470,554, reverse strand). Ensembl gene ENSG00000017483.
Subcellular location: Cell membrane
Subcellular location (Human Protein Atlas): Plasma membrane; Vesicles; Cytosol
Pathways (Reactome):
Transport of small molecules: Amino acid transport across the plasma membrane
Gene Ontology:
Molecular function: alanine transmembrane transporter activity; glycine transmembrane transporter activity; L-asparagine transmembrane transporter activity; L-glutamine transmembrane transporter activity; L-histidine transmembrane transporter activity; L-serine transmembrane transporter activity; neutral amino acid, sodium:proton antiporter activity; amino acid transmembrane transporter activity; L-glutamine, sodium:proton antiporter activity
Biological process: asparagine transmembrane transport; glutamine transport; glycine transport; L-alanine transmembrane transport; L-histidine transmembrane transport; neutral amino acid transport; serine transport; amino acid export across plasma membrane; amino acid import across plasma membrane; amino acid transport; L-glutamine import across plasma membrane; L-serine import across plasma membrane; L-serine transport; transport across blood-brain barrier; asparagine transport; sodium ion transmembrane transport
Cellular component: plasma membrane
Homologues: Orthologues: chimpanzee SLC38A5 (99% identical), macaque SLC38A5 (97% identical), pig SLC38A5 (92% identical), dog SLC38A5 (89% identical), rabbit SLC38A5 (88% identical), rat Slc38a5 (88% identical), mouse Slc38a5 (88% identical), zebrafish slc38a5a (60% identical), tropical clawed frog slc38a5 (60% identical), Drosophila melanogaster CG32079 (20% identical), Caenorhabditis elegans slc-36.3 (16% identical), Drosophila melanogaster CG13384 (16% identical), and 14 more. Paralogues in human: SLC38A3 (62% identical), SLC38A4 (52% identical), SLC38A2 (51% identical), SLC38A1 (46% identical), SLC38A6 (42% identical), SLC38A10 (22% identical), SLC38A11 (21% identical), SLC32A1 (20% identical), SLC36A4 (20% identical), SLC38A8 (20% identical), SLC38A9 (19% identical), SLC38A7 (19% identical), and 3 more.
Diseases named in the same sentence as SLC38A5 in open-access papers:
SLC38A5 is named in the same sentence as 37 diseases in open-access papers, as found by Europe PMC text mining. Sharing a sentence is not in itself a finding about the gene and the disease. The quoted sentences say what the papers report.
breast carcinoma (8 papers, 2021 to 2025). "Our recent studies with breast cancer cell lines have demonstrated that niclosamide causes intracellular acidification and also inhibits SLC38A5, both leading to the suppression of macropinocytosis." (PMID 38891084, 2024). "In addition, SLC38A5 is highly expressed in breast cancer tissues and is associated with lower patient survival rates." (PMID 39973065, 2025). "It has been demonstrated that SLC1A5, SLC6A14, SLC7A11, SLC3A1, SLC7A5, SLC38A2, and SLC38A5 are significantly expressed in breast cancer cells." (PMID 39973065, 2025). "Niclosamide, an anti-tapeworm drug, has been shown to inhibit SLC38A5 activity in breast cancer cells by blocking H+ efflux, resulting in intracellular acidification." (PMID 39973065, 2025). "Silencing SLC38A5 inhibits tumor growth in murine breast cancer models and increases BC cell sensitivity to cisplatin." (PMID 39973065, 2025). "Based on our previous studies with breast cancer cells, the ability of niclosamide to induce intracellular acidification and inhibit SLC38A5 is expected to suppress macropinocytosis." (PMID 38891084, 2024). "Recently, we found that the amino acid transporter SLC38A5, which functions as an amino-acid-dependent Na+/H+ exchanger, is also able to induce macropinocytosis in breast cancer cells." (PMID 38891084, 2024). "The present investigation focuses on the expression of SLC38A5 in breast cancer." (PMID 34704597, 2021). "We monitored macropinocytosis in pancreatic and breast cancer cells using TMR-dextran and the function of SLC38A5 by measuring Li+-stimulated serine uptake." (PMID 36765717, 2023). "Dual targeting of SLC6A14 with SLC25A15, SLC12A4, SLC1A5 and SLC38A5 also reduced growth in MCF7 and MDA-MB-231 human breast cancer cell lines." (PMID 38066114, 2023). "We first examined primary tumor specimens from patients with ER+ breast cancer and TNBC for expression of SLC6A14 and SLC38A5." (PMID 34704597, 2021). "Further studies revealed that pretreatment of TNBC cells with niclosamide reduces the protein expression of SLC38A5 and SLC7A11, induces oxidative stress, lipid peroxidation, and ferroptosis, and significantly suppresses breast cancer growth in mouse xenograft models." (PMID 39973065, 2025). "The up-regulation of SLC38A5 was evident in breast cancer samples as well as cell lines, and silencing of SLC38A5 attenuated cell proliferation in TNBC cells accompanied by reduced micropinocytosis, suggesting the oncogenic role of SLC38A5 in TNBC." (PMID 35518353, 2022). "Even though SLC38A3 exhibits functional features that are almost identical with those of SLC38A5, the expression of the former is actually decreased in breast cancer, and the decrease is independent of the hormone receptor status of the tumor (TCGA database)." (PMID 34704597, 2021). "Given that SLC38A5 as well as SLC38A2 might have relevance to breast cancer growth and progression, we analyzed the expression of these two transporters in breast cancer using the TCGA (The Cancer Genome Atlas) database." (PMID 34704597, 2021).
pancreatic cancer (7 papers, 2022 to 2025). "ABC transporters and SLC38A5 have been associated with drug resistance to cisplatin and gemcitabine in breast and pancreatic cancer, respectively." (PMID 40595509, 2025). "Collectively, SLC38A5 inhibition sensitizes drug-resistant pancreatic cancer cells to gemcitabine by inducing ferroptosis and suppressing tumor growth and metastasis." (PMID 37887353, 2023). "In summary, we believe that targeting SLC38A5 will significantly contribute to the treatment of patients with gemcitabine-resistant pancreatic cancer and improve their 5-year survival rate." (PMID 37887353, 2023). "To investigate SLC38A5 expression in pancreatic cancer cells, we analyzed mRNA and protein levels in human pancreatic cancer cell lines." (PMID 37887353, 2023). "In the current study, a total of 17 genes with prognostic values have been identified, of which 8 genes (SFXN5, LRRC8E, KCNJ10, UPB1, SLC43A2, SLC38A10, ACCS, and SLC38A5) were identified for the first time in pancreatic cancer." (PMID 37333498, 2023). "Taken together, our results suggest that SLC38A5 is a novel therapeutic target for ameliorating gemcitabine resistance in pancreatic cancer." (PMID 37887353, 2023). "We examined the expression of SLC38A5 in pancreatic cancer using RT-PCR, Western blotting, and immunohistochemical staining." (PMID 37887353, 2023). "According to The Cancer Genome Atlas (TCGA) database, upregulation of SLC38A5 tends to result in a poor survival rate in pancreatic cancer." (PMID 37887353, 2023). "Based on these experiments, we found that pancreatic tumor tissues have higher expression levels of SLC38A5 than normal tissues." (PMID 37887353, 2023). "Analysis of data available at the Cancer Genome Atlas (TGCA) reveals that SLC38A5 is upregulated not only in triple-negative breast cancer but also in pancreatic cancer." (PMID 35204736, 2022). "In fact, the levels of SLC38A5 expression correlate reciprocally with the survival of the patients with pancreatic cancer." (PMID 35204736, 2022). "To elucidate the role of SLC38A5 in gemcitabine resistance, we established gemcitabine-resistant pancreatic cancer cell lines using PANC-1 and Capan-1 cells (PANC-GR and Capan-GR, respectively) by confirming the half-maximal inhibitory concentration (IC50) via a cell viability test." (PMID 37887353, 2023). "Moreover, SLC38A5 inhibition effectively sensitized pancreatic cancer cells to gemcitabine treatment, suppressing tumor weight and metastasis in vivo." (PMID 37887353, 2023). "To evaluate whether SLC38A5 plays an important role in the metastasis of gemcitabine-resistant pancreatic tumors in vivo, we generated a BALB/c nude mouse model bearing orthotopic tumors." (PMID 37887353, 2023). "Therefore, targeting SLC38A5 may play a major role in improving the 5-year survival rate of patients with pancreatic cancer and overcoming chemoresistance in pancreatic cancer for clinical purposes." (PMID 37887353, 2023). "Therefore, targeting SLC38A5 may be a promising therapeutic agent for improving the survival rate of patients with gemcitabine-resistant pancreatic cancer." (PMID 37887353, 2023). "Therefore, we hypothesized that there could be a crucial role of SLC38A5 in pancreatic cancer." (PMID 37887353, 2023). "Both SLC38A5 and RRM1 mRNA levels were higher in gemcitabine-resistant pancreatic cancer tissues than in gemcitabine-sensitive patient tissues." (PMID 37887353, 2023). "In the present study, we expanded our investigation of SLC38A5 expression in TNBC to additional cell lines and also to a couple of representative pancreatic cancer cell lines." (PMID 36765717, 2023). "Moreover, increased levels of SLC38A5 tended to decrease the overall survival (OS) and disease-specific survival (DSS) of patients with pancreatic cancer." (PMID 37887353, 2023). "Similarly, the protein levels of both SLC38A5 and RRM1 were increased in drug-resistant pancreatic cancer patients compared with those in the drug-sensitive group." (PMID 37887353, 2023).
pancreatic cancer (continued). "Therefore, we confirmed that SLC38A5 is involved in the proliferation and EMT of gemcitabine-resistant pancreatic cancer cells." (PMID 37887353, 2023). "However, there have been no studies on the biological mechanisms of SLC38A5 and gemcitabine resistance in pancreatic cancer." (PMID 37887353, 2023).
osteosarcoma (4 papers, 2022 to 2026). A usually aggressive malignant bone-forming mesenchymal neoplasm, predominantly affecting adolescents and young adults. "SLC38A5 expression was up-regulated in high-risk group than that in low-risk group, and Kaplan-Meier survival analysis in two independent cohorts revealed that higher expression of SLC38A5 predicted worse overall survival in osteosarcoma." (PMID 35518353, 2022). "This study highlights SLC38A5-mediated glutamine metabolism as a critical determinant of metastatic potential and supports melatonin and SLC38A5 as promising therapeutic targets for osteosarcoma and chondrosarcoma." (PMID 42212332, 2026). "However, up to now, little is known about the involvement of SLC38A5 in osteosarcoma and other cancers." (PMID 35518353, 2022). "Our findings suggest that SLC38A5 may act as an oncogene in osteosarcoma, and its role has to be investigated further in vitro and in vivo." (PMID 35518353, 2022). "However, SLC38A5 as a drug target for osteosarcoma would require further investigations." (PMID 36578780, 2022). "The expression of BNIP3, SLC38A5, CKMT2, CXCL11, SLC5A3, S100A3, and PGM1 genes was verified in osteosarcoma cells (Saos-2 and 143B) and normal osteoblasts (hFOB1.19)." (PMID 36578780, 2022).
colorectal cancer (3 papers, 2022 to 2025). A primary or metastatic malignant neoplasm that affects the colon or rectum. "Combination of SLC6A14 with SLC1A5 or SLC38A5 had a larger effect in breast versus colorectal cancer cell lines, likely reflecting that tissue of origin can influence SLC substrate selectivity." (PMID 38066114, 2023). "In conclusion, CDH17 plays a crucial role in maintaining colorectal cancer cell stemness and chemoresistance via LGR5/Wnt/MYC signaling and SLC38A5 expression." (PMID 40595509, 2025).
triple-negative breast carcinoma (3 papers, 2021 to 2024). An invasive breast carcinoma which is negative for expression of estrogen receptor (ER), progesterone receptor (PR), and human epidermal growth factor receptor 2 (HER2). "Since triple-negative breast cancer cells express high levels of SLC38A5, the connection of this transporter to macropinocytosis was investigated in these cells." (PMID 35204736, 2022). "Here, we report on the differential up-regulation of the amino acid transporter SLC38A5 in triple-negative breast cancer (TNBC)." (PMID 34704597, 2021). "The amino acid transporters SLC38A5 and SLC7A11 are upregulated in triple-negative breast cancer (TNBC)." (PMID 38539825, 2024).
exudative vitreoretinopathy (2 papers, 2022 to 2024). Familial exudative vitreoretinopathy (FEVR) is a rare hereditary vitreoretinal disorder characterized by abnormal or incomplete vascularization of the peripheral retina leading to variable clinical manifestations ranging from no effects to minor anomalies, or even retinal detachment with blindness. "Previous research revealed that Slc38a5 was significantly decreased in both Lrp5−/− and Ndpy/− retinas, which are experimental models of familial exudative vitreoretinopathy (FEVR) and Norrie disease, respectively, two genetic vascular eye diseases with inadequate retinal vasculature." (PMID 39335451, 2024).
bone cancer (1 paper, 2026). A primary or metastatic malignant neoplasm affecting the bone or articular cartilage. "Notably, solute carrier family 38 member 5 (SLC38A5), a glutamine transporter, was identified as a critical regulator of bone cancer progression, with higher SLC38A5 expression correlating with poorer clinical outcomes." (PMID 42212332, 2026).
breast tumor (1 paper, 2021). "We found the expression of SLC38A5 to be significantly higher in primary breast tumor tissues than in normal breast tissue." (PMID 34704597, 2021).
colon cancer (1 paper, 2024). "The role of SLC38A5 in colon cancer has not yet been investigated even though it is expressed in the intestinal tract." (PMID 38891084, 2024).
developmental delay (1 paper, 2024). "Regarding the top10 from the group comparisons in brain samples (studies GSE102204 & GSE154106), we want to highlight the chemokine Ccl21a which was also related to neurological diseases and Slc38a5 which has been shown to cause developmental delay in motor dysfunction." (PMID 39529156, 2024).
diabetic retinopathy (1 paper, 2022). "To evaluate the role of Slc38a5 in pathological retinal angiogenesis, we used a well-established OIR model, mimicking the hypoxia-induced proliferative phase as seen in retinopathy of prematurity and diabetic retinopathy." (PMID 36454214, 2022).
metabolic syndrome (1 paper, 2022). A cluster of metabolic risk factors for CARDIOVASCULAR DISEASES and TYPE 2 DIABETES MELLITUS. "In the present review, we highlight the unusual involvement of selective amino acid transporters in macropinocytosis (SLC38A5/SLC38A3) and diet-induced obesity/metabolic syndrome (SLC6A19/SLC6A14/SLC6A6)." (PMID 35204736, 2022). "The recent discovery of the role of SLC38A5 in promoting macropinocytosis and the contrasting roles of SLC6A19 and SLC6A14 in diet-induced obesity and metabolic syndrome highlights these novel and unconventional functions of specific amino acid transporters." (PMID 35204736, 2022).
pancreatic ductal adenocarcinoma (1 paper, 2025). An infiltrating adenocarcinoma that arises from the epithelial cells of the pancreas. "Inhibition of SLC38A5 triggers ferroptosis signaling in pancreatic ductal adenocarcinoma by downregulating GSH levels and GSH‐related genes." (PMID 40181576, 2025).
pregnancy diseases (1 paper, 2018). "Our work reports for the first time that SLC38A5 is differentially regulated (increased) at mRNA level in the clinically highly relevant pregnancy diseases IUGR and PE." (PMID 29499643, 2018).
retinal diseases (1 paper, 2022). "Whether SLC38A5 may regulate serine transportation to influence retinal AA metabolism, angiogenesis, and retinal diseases will need additional investigation." (PMID 36454214, 2022).
selenium deficiency (1 paper, 2024). A nutritional deficiency disease resulting from inadequate selenium levels in the body, which can lead to impaired function of selenoproteins essential for antioxidant defense and thyroid hormone metabolism. "Therefore, we speculate that since the expression and function of SLC38A5 are drastically suppressed by niclosamide in TNBC cells, it would cause selenium deficiency due to impaired Se-Met delivery, which would then be expected to decrease the stability of GPX4 mRNA and hence its protein levels." (PMID 38539825, 2024).